COL11A1 (collagen type XI alpha 1 chain)
Diseases named in the same sentence as COL11A1 in open-access papers (continued):
Sharing a sentence is not in itself a finding about the gene and the disease.
melanoma (7 papers, 2013 to 2022). A malignant, usually aggressive tumor composed of atypical, neoplastic melanocytes. "Studies disclosed that methylation of genes like APC, PYCARD, and COL11A1 is relevant to the incidence of melanoma, and histone H3K27me3 upregulation can promote melanoma progression." (PMID 36060650, 2022). "By contrast, COL11A1 was expressed intensely by melanoma cells located in the dermis of both primary and metastatic melanoma." (PMID 23638386, 2013). "Third, we validated the expression of MAPK-associated members (COL11A1, CXCL13, PTPRF, SHC4) of the 12-gene biomarkers in a comparative analysis of normal melanocytes and melanoma cells in vitro and in primary versus metastatic melanoma biopsy tissue in situ." (PMID 23638386, 2013). "While SHC4 has been reported previously to be associated to melanoma, this is the first time CXCL13, COL11A1, and PTPRF have been associated with melanoma on experimental validation." (PMID 23638386, 2013). "This leaves WNT4, CHP2, PPP2R2C and COL11A1 which have not been previously reported to be associated with melanoma." (PMID 23638386, 2013). "Specifically, genes upregulated or downregulated in response to UV radiation involve CDKN1C, CDK2, COL11A1, KIT, and IGF1R, the majority of which are identified as differentially upregulated in melanoma versus atypical tumor or nevus." (PMID 35052351, 2021). "The over-expression of COL11A1, CXCL13, PTPRF and SHC4 in our melanoma cell lines and primary and metastatic tissue, and their potential association with MAPK pathways suggests they could be specific biomarkers for melanoma and so potential therapeutic targets." (PMID 23638386, 2013). "COL11A1, CXCL13, PTPRF, and SHC4 were found to be over-expressed in two human melanoma cell lines (i.e., FM55 and FM94) compared to normal human epidermal melanocytes in vitro." (PMID 23638386, 2013). "Note that COL11A1, CXCL13, and PTPRF have not previously been reported to be associated with melanoma experimentally." (PMID 23638386, 2013). "The over-expression of COL11A1, CXCL13, PTPRF, and SHC4 in melanoma cells in vitro and in situ may reflect the observed over-expression of the associated genes in our microarray meta-analysis results." (PMID 23638386, 2013). "However, six signature genes (i.e., IL8, SHC4, COL11A1, CHP2, PPP2R2C and WNT4) were not reported previously by microarray-based melanoma studies, although two (i.e. IL8 and SHC4) have been identified in independent wet-lab studies." (PMID 23638386, 2013).
serous ovarian cancer (7 papers, 2014 to 2023). "For example, one study analyzed three large microarray datasets in serous ovarian cancer, and reported a 10-gene signature that are associated with poor OS, which included COL11A1 and could be regulated by TGF-signaling." (PMID 36744260, 2023). "Consistently, elevated COL11A1 expression is also a predictor for poor survival in patients with serous ovarian cancer." (PMID 33026975, 2020).
deafness (6 papers, 2013 to 2025). An inherited or acquired condition characterized by the complete loss of the ability to hear from one or both ears. "The most significantly associated gene is COL11A1, a known non-syndromic and syndromic deafness gene that encodes type XIα collagen, identified within the lattice of the tectorial membrane, a gelatinous structure atop the Organ of Corti and in supporting Deiter’s Cells 48–50." (PMID 38242899, 2024). "Until now, pathogenic variants in COL11A1 have been exclusively linked to syndromic deafness." (PMID 30245514, 2019). "In summary, here we report the clinical and genetic characteristics associated with deafness at the DFNA37 locus and we expand the spectrum of COL11A1-associated phenotypes to include ADNSHL." (PMID 30245514, 2019). "TECTA, WFS-1, MYH9, EYA1, COL4A5, COL11A1 were identified as the responsible genes for deafness in autosomal dominant families." (PMID 23967202, 2013). "We have identified COL11A1 as the gene responsible for deafness at the DFNA37 locus." (PMID 30245514, 2019). "TMPRSS3, MYO15A, GJB2, SLC26A4 were found to be responsible for deafness in autosomal recessive or sporadic families, while TECTA, WFS1, MYH9, EYA1, COL4A5 and COL11A1 were identified as the responsible genes for deafness in autosomal dominant families." (PMID 23967202, 2013).
head and neck squamous cell carcinoma (6 papers, 2017 to 2025). A squamous cell carcinoma that arises from any of the following anatomic sites: lip and oral cavity, nasal cavity, paranasal sinuses, pharynx, larynx, and salivary glands. "In head and neck squamous cell carcinoma cells, COL11A1 facilitated their proliferation, migration and invasion." (PMID 28331057, 2017).
cleft palate (5 papers, 2019 to 2024). Cleft palate is a fissure type embryopathy that affects the soft and hard palate to varying degrees. "COL11A1 is also an alternatively spliced gene, however, pathogenic variants in humans result in additional systemic anomalies that can include cleft palate, deafness, hypermobility and arthropathy." (PMID 38153936, 2023). "Specific to skeletal dysplasia, pathogenic variants in genes encoding type II and XI collagen (COL2A1, COL11A1 and COL11A2), Filamin-A (FLNA), and the diastrophic sulfate transport protein (SLC26A2) are all well-known as being associated with cleft palate." (PMID 33446226, 2021). "Previously, two different studies has proposed that major clefting locus might be located at 6p and mutation in several genes such as COL2A1, COL11A1, and COL11A2 caused syndrome that was associated with cleft palate, Robin sequence, and micrognathia." (PMID 30924295, 2019). "On the other hand, it has also been found that the COL2A1, COL11A1, and COL11A2 were associated and influence the risk of nonsyndromic forms of cleft palate." (PMID 30924295, 2019).
lymph node metastasis (5 papers, 2015 to 2025). "However, expressions of COL11A1 have shown associations with prognostic factors, pathological stages, and lymph node metastasis in non-small cell lung cancer (NSCLC) in some previous studies." (PMID 31987030, 2020). "COL11A1 protein expression was evaluated by Western blot in six matched trios of normal tissue, primary cancer, and lymph node metastasis." (PMID 39845732, 2025).
pancreatic ductal adenocarcinoma (5 papers, 2021 to 2022). An infiltrating adenocarcinoma that arises from the epithelial cells of the pancreas. "Genome-wide transcriptional analysis in human pancreatic ductal adenocarcinoma identified that activated pancreatic stellate cells are yet one more type of cancer-associated cells that overexpress COL11A1." (PMID 33668097, 2021). "Previous reports indicate that COL11A1 may be a significant diagnostic marker for pancreatic ductal adenocarcinoma (PDAC); however, its biological role in PDAC progression remains unclear." (PMID 35327583, 2022). "Collagen XI, a member of the collagen family, is present in the extracellular matrix (ECM), and high collagen XI/αI (COL11A1) expression in tumor tissue is reportedly correlated with the clinicopathological parameters of pancreatic ductal adenocarcinoma (PDAC)." (PMID 33531986, 2021).
cutaneous squamous cell carcinoma (4 papers, 2021 to 2025). "Here we identify COL11A1 mutations in 66 of 100 cutaneous squamous cell carcinomas (cSCCs), the second most common U.S. cancer, concentrated in a triple helical region known to produce trans-dominant collagens." (PMID 34584216, 2021). "Previous reports have shown that mutant COL11A1 promotes tumorigenesis and cancerous invasion in cutaneous squamous cell carcinoma." (PMID 38293522, 2024). "COL11A1 promotes invasion in cutaneous squamous cell carcinoma." (PMID 39845732, 2025). "COL11A1 missense variants, usually altering glycine or proline in Gly-X-Y repeats in the collagen α1(XI) helical domain as with COL11A1P1335L, are reported to be frequent in cutaneous squamous cell carcinomas and have been linked to transcriptional changes and tumor invasiveness." (PMID 38277211, 2024).
disc degeneration (4 papers, 2012 to 2024). "Compared to CC or CT genotype, the TT genotype carriers had remarkedly decreased COL11A1 mRNA expression in disc tissues and higher grade of severity of disc degeneration." (PMID 34663366, 2021). "The rs1676486 T-allele has been reported to result in decreased synthesis and stability of COL11A1 mRNA suggesting a functional importance in disc degeneration." (PMID 23185509, 2012). "COL11A1 (rs1676486) C/C genotype protective against disc degeneration." (PMID 39200631, 2024).
invasive carcinoma (4 papers, 2017 to 2025). A carcinoma that is not confined to the epithelium, and has spread to the surrounding stroma. "However these two minor downregulated collagens are indeed both known to be involved in cancer: COLA4A is upregulated by p5358 and COL11A1 is a biomarker of invasive carcinoma-associated cells." (PMID 39009698, 2024). "Interestingly, in invasive carcinomas, high expression of COL11A1 is detected in the stroma of breast, colorectal, esophagus, glioma, gastric, lung, ovarian, pancreatic and salivary gland cancers." (PMID 33668097, 2021). "COL11A1 has also been found to be expressed at the front of invasive carcinomas by presumably carcinoma cells, putatively undergoing epithelial-to-mesenchymal (EMT) transition; also, carcinoma-derived cells with highly metastatic capabilities can express COL11A165." (PMID 28743863, 2017).
osteosarcoma (4 papers, 2012 to 2025). A usually aggressive malignant bone-forming mesenchymal neoplasm, predominantly affecting adolescents and young adults. "The upregulation of COL11A1 and SFRP2 has been reported in human osteosarcoma." (PMID 35456486, 2022).
tendinopathy (4 papers, 2016 to 2023). "COL11A1 and A2 variants have also been studied in relation to tendinopathy, although to a lesser extent." (PMID 32300121, 2020). "However, while the mRNA expression of a number of collagens was 1.6–2.7-fold upregulated in tendinopathy patients, COL1A1, COL1A2, COL10A1, and COL11A1/2 were 5.3–15.2-fold upregulated in tetraplegic CP patients, suggesting strongly increased collagen synthesis." (PMID 38001919, 2023).
brain cancer (3 papers, 2017 to 2024). A primary or metastatic malignant neoplasm affecting the brain. "Many studies had highlighted the importance of COL11A1 in multiple types of cancer, including colorectal, ovarian, breast, head and neck, lung, and brain cancers." (PMID 28393072, 2017).
chronic pancreatitis (3 papers, 2013 to 2021). A chronic inflammatory process causing damage and fibrosis of the pancreatic parenchyma. "The focal pattern of COL11A1 staining is restricted to defined areas of PDAC/CAF interaction while absent in chronic pancreatitis, which suggests that its expression is highly dependent on local factors coming from the neighboring carcinoma cells." (PMID 24194920, 2013). "COL11A1/procollagen 11A1 expression is mostly absent in benign inflammatory processes such as breast sclerosing adenosis, chronic pancreatitis, and diverticulitis (our own observations; data not shown), and is rather low in familial adenomatosis polyposis adenomas." (PMID 25417197, 2014).
collagenopathies (3 papers, 2021 to 2025). "Pathogenic variants for collagenopathy were uncovered in 10/12 children: COL11A1 (heterozygous) in six, COL2A1 (heterozygous) in two, and COL9A1 (homozygous) in two." (PMID 33951325, 2021). "Bilateral RRD was only seen in collagenopathies/vitreoretinopathies with COL2A1 (n = 2, 33.3%), COL11A1 (n = 1, 16.7%), COL18A1 (n = 1, 16.7%) and FBN1 (n = 2, 33.3%) genotypes." (PMID 41465105, 2025). "If collagenopathies (COL2A1, COL11A1, COL18A1) and Marfan syndrome are removed, this figure (n = 3/401, 0.7%) remains 70× the population risk." (PMID 41465105, 2025).
colonic carcinomas (3 papers, 2014 to 2023). "Following this, outcomes of CCK-8 and colony formation methods discovered that COL11A1 inhibition remarkably suppressed the viability and colony formative ability of colon carcinoma cells." (PMID 35669376, 2022). "The roles of COL11A1 in cancer have been increasingly considered, but the understandings of the effects of COL11A1 on colon carcinoma progress are much limited yet." (PMID 35669376, 2022). "CCK-8 assay showed that COL11A1 overexpression remarkably promoted viability of colon carcinoma cells, yet the promotion was repressed by simultaneously overexpressing miR-339-5p." (PMID 35669376, 2022). "COL11A1 upregulation promoted colon carcinoma cell functions, while overexpressing miR-339-5p evidently attenuated the promotion." (PMID 35669376, 2022). "COL11A1 expression was prominently upregulated in colon carcinoma cell lines relative to that in normal human colon mucosal epithelial cell lines, and it was related to tumor stages." (PMID 35669376, 2022). "Here, COL11A1 expression was measured in colon carcinoma, and the relationship between COL11A1 and miR-339-5p was researched." (PMID 35669376, 2022). "Nevertheless, far less has been studied on the effects of COL11A1 on the malignant progression of colon carcinoma." (PMID 35669376, 2022). "MiR-339-5p suppressed cancer via downregulating COL11A1 expression, and COL11A1 promoted colon carcinoma progression." (PMID 35669376, 2022). "Based on the experimental data, COL11A1 was confirmed as a downstream target of miR-339-5p in colon carcinoma." (PMID 35669376, 2022). "qRT-PCR and Western blot were utilized to evaluate COL11A1 expression at mRNA and protein levels, respectively, in colon carcinoma cell lines." (PMID 35669376, 2022). "As shown in mRNA expression data in the TCGA-COAD dataset, COL11A1 expression was upregulated in colon carcinoma tissue than that in adjacent normal tissue." (PMID 35669376, 2022). "To explore whether miR-339-5p participates in regulating colon carcinoma cells via targeting COL11A1, we constructed miR-NC + oe-NC, miR-NC + oe-COL11A1, and miR-mimics + oe-COL11A1 groups." (PMID 35669376, 2022). "Likewise, the COL11A1 expression level in different colon carcinoma cell lines was confirmed through qRT-PCR and western blot, indicating that COL11A1 was remarkably upregulated in colon carcinoma cell lines with normal cell lines as the control." (PMID 35669376, 2022). "We interfered with COL11A1 expression in colon carcinoma cell lines SW620 and SW480." (PMID 35669376, 2022). "Several previous works pointed out high COL11A1 expression in colon carcinoma tissues." (PMID 35669376, 2022). "Besides, qRT-PCR assay manifested that miR-339-5p overexpression declined COL11A1 expression in colon carcinoma cells." (PMID 35669376, 2022). "However, no study has reported the effect of COL11A1 and the way the miR-339-5p/COL11A1 axis worked in colon carcinoma." (PMID 35669376, 2022). "The miR-339-5p/COL11A1 regulatory axis could participate in colon carcinoma progression and may be used as a potential therapeutic indicator." (PMID 35669376, 2022). "Therefore, miR-339-5p restrained colon carcinoma cell behaviors by targeting COL11A1." (PMID 35669376, 2022).
colorectal tumor (3 papers, 2009 to 2015). "COL11A1 mRNA was also found increased in NBCCS fibroblasts, an observation reminiscent of its over-expression by stromal fibroblasts in human colorectal tumors." (PMID 19287498, 2009).
head and neck cancer (3 papers, 2015 to 2025). A primary or metastatic malignant neoplasm affecting the head and neck. "In this study, we investigate the association between the tumor mutational burden (TMB) and clinical characteristics of HNSCC, as well as the impact of COL11A1 gene mutations on the immune microenvironment in head and neck cancer (HNC)." (PMID 40322427, 2025).
Hip dysplasia (3 papers, 2019 to 2024). The presence of developmental dysplasia of the hip. "Three OES, one homozygous and two heterozygous for the COL11A1 variant were diagnosed with hip dysplasia." (PMID 38153936, 2023). "Previous studies suggested collagen XI alpha 1 (COL11A1) as a potential gene in hip dysplasia and chondrocyte degeneration." (PMID 38314968, 2024). "COL11A1 dysregulation was also found in incipient canine hip dysplasia." (PMID 38314968, 2024).
invasive breast carcinoma (3 papers, 2011 to 2025). A carcinoma that infiltrates the breast parenchyma. "Given that the expression level of COL11A1 is closely related to the poor prognosis and immune infiltration of invasive breast cancer patients." (PMID 36160004, 2022). "Stromal reaction to invasive breast carcinoma was associated with increased expression of genes encoding ECM components, proteolytic enzymes and adhesion receptors, including COL11A1, COL10A1, COMP, MMP11, FN1 and MFAP2, consistent with the abundant stromal remodeling observed by histology." (PMID 21611158, 2011). "To explore the difference in COL11A1 protein expression levels, we used UALCAN online tool to analyze invasive breast cancer and normal breast tissue samples from the CPTAC database." (PMID 36160004, 2022).
lung fibrosis (3 papers, 2022 to 2025). "This revealed an overall increased deposition by AFs of collagen family members (COLs, including COL4A1 and COL11A1), fibrillins (FBN1 and 2) and tenascin (TNC), previously involved in lung fibrosis and deposited by CAFs in other cancers." (PMID 37938546, 2023).
metastatic tumors (3 papers, 2021 to 2025). "Expression of COL2A1, COL11A1, COL6A1, COL6A2 and LUM tended to be higher in primary/metastatic tumor than in normal tissue." (PMID 40927672, 2025).
otospondylomegaepiphyseal dysplasia (3 papers, 2020 to 2025). An inborn error of cartilage collagen formation characterized by sensorineural hearing loss, enlarged epiphyses, skeletal dysplasia with disproportionately short limbs, vertebral body anomalies and a characteristic facies. "Type 2 SS and the SS variant otospondylomegaepiphyseal dysplasia (OSMED) are caused by deleterious variants in COL11A1 and COL11A2, respectively." (PMID 33348901, 2020).
renal cell carcinoma (3 papers, 2021 to 2024). "When looking at the top 10 upregulated genes, we found for example Ccdc180, Col11a1, Gria2, or Prdm6 in males in relation to regulation of transcription, renal cell carcinoma, and fibrosis." (PMID 35230975, 2022).
sarcoma (3 papers, 2021 to 2025). A usually aggressive malignant neoplasm of the soft tissue or bone. "COL11A1-CAR T cells recognized and killed COL11A1-positive tumor cells in vitro and had potent antitumor activity in vivo in two pediatric sarcoma xenograft models." (PMID 38702309, 2024).
Type I Stickler syndrome (3 papers, 2012 to 2025). "Type I Stickler syndrome (STL1) is associated with mutations in the COL2A1 gene encoding type II collagen, while mutations in COL11A1 and COL11A2 encoding type XI collagen, are associated with type II (STL2) and type III Stickler syndrome (STL3) respectively." (PMID 23110709, 2012).
autism spectrum disorder (2 papers, 2021 to 2025). A spectrum of developmental disorders that includes autism, and Asperger syndrome. "In this study, through the analysis of CHD8A and CHD8B allelic deletion samples, we identified seven hub genes associated with Autism Spectrum Disorder (ASD): IGF2, FN1, CXCR4, COL11A1, ITGA6, LOX, and FBN2." (PMID 40526590, 2025).
breast intraductal papilloma (2 papers, 2015 to 2019). "COL11A1 could be utilized as a promising biomarker in predicting malignant relapse of breast intraductal papilloma." (PMID 30746900, 2019). "To conclude, the expression of COL11A1 in breast intraductal papillomas is an optimal prognostic biomarker, and we propose that patients with positive staining for this protein should be given further evaluation of both surgical treatment and preventive adjuvant chemotherapy." (PMID 26448946, 2015).